CBS (cystathionine beta-synthase)
Description:
Hydro-lyase catalyzing the first step of the transsulfuration pathway, where the hydroxyl group of L-serine is displaced by L-homocysteine in a beta-replacement reaction to form L-cystathionine, the precursor of L-cysteine. This catabolic route allows the elimination of L-methionine and the toxic metabolite L-homocysteine. Also involved in the production of hydrogen sulfide, a gasotransmitter with signaling and cytoprotective effects on neurons (By similarity).
Synonyms: HIP4
Tractability: Small molecule: a structure with a bound ligand is known; a high-quality ligand is known; it has a high-quality binding pocket. PROTAC: UniProt records ubiquitination sites on it; ubiquitination databases record sites on it; its protein half-life has been measured; a small molecule that binds it is known.
Target class: Enzyme
Gene: Protein-coding gene on chromosome 21 (43,050,900 to 43,076,943, reverse strand). Ensembl gene ENSG00000160200.
Subcellular location: Cytoplasm; Nucleus
Subcellular location (Human Protein Atlas): Vesicles; Nucleoli
Pathways (Reactome):
Metabolism: Cysteine formation from homocysteine; Metabolism of ingested SeMet, Sec, MeSec into H2Se
Gene Ontology:
Molecular function: carbon monoxide binding; cystathionine beta-synthase activity; enzyme binding; heme binding; identical protein binding; modified amino acid binding; nitric oxide binding; nitrite reductase (NO-forming) activity; oxygen binding; protein binding; protein homodimerization activity; pyridoxal phosphate binding; S-adenosyl-L-methionine binding; ubiquitin protein ligase binding
Biological process: cysteine biosynthetic process; DNA protection; homocysteine catabolic process; homocysteine metabolic process; hydrogen sulfide biosynthetic process; L-cysteine catabolic process; L-serine catabolic process; L-serine metabolic process; cellular response to hypoxia; cellular response to insulin stimulus; L-amino acid metabolic process; negative regulation of apoptotic process; response to nutrient levels; sulfur compound biosynthetic process; transsulfuration
Cellular component: cytoplasm; cytosol; nucleus
Gene-disease validity (ClinGen):
ClinGen rates the evidence that CBS causes each of these diseases.
classic homocystinuria (autosomal recessive): Definitive. Classical homocystinuria due to cystathionine beta-synthase (CbS) deficiency is characterized by the multiple involvement of the eye, skeleton, central nervous system, and vascular system.
Homologues: Orthologues: chimpanzee CBS (99% identical), dog CBS (89% identical), pig CBS (88% identical), mouse Cbs (84% identical), rat Cbs (84% identical), rabbit CBS (83% identical), guinea pig CBS (83% identical), macaque CBS (78% identical), tropical clawed frog cbs (75% identical), zebrafish cbsb (75% identical), zebrafish cbsa (74% identical), Drosophila melanogaster Cbs (48% identical), and 2 more. Paralogues in human: SRR (17% identical), SDSL (15% identical), THNSL1 (14% identical), SDS (14% identical), THNSL2 (13% identical).
Diseases named in the same sentence as CBS in open-access papers:
CBS is named in the same sentence as 318 diseases in open-access papers, as found by Europe PMC text mining. Sharing a sentence is not in itself a finding about the gene and the disease. The quoted sentences say what the papers report.
homocystinuria (110 papers, 2005 to 2026). An autosomal recessive inherited metabolic disorder caused by mutations in the CBS, MTHFR, MTR, and MTRR genes. "Cystathionine β-synthase (CBS) deficiency causes classical homocystinuria with severe hyperhomocysteinemia (HHcy) that is inadequately controlled by current therapies." (PMID 41977510, 2026). "Mutations in the CBS gene, encoding cystathionine beta-synthase, can lead to enzyme activity deficiency and an autosomal recessive metabolic disorder known as classical homocystinuria." (PMID 40650005, 2025). "Homocystinuria due to cystathionine beta‐synthase (CBS) deficiency is a rare metabolic disorder inherited as an autosomal recessive trait." (PMID 39839200, 2025). "Classic homocystinuria, a rare congenital metabolic disorder caused by cystathionine beta synthase (CBS) enzyme deficiency, was associated with high blood Hcy concentration, thromboembolic tendency, and neurocognitive symptoms." (PMID 40299504, 2025). "The most common cause of inherited homocystinuria is cystathionine beta-synthase (CBS) (EC 4.2.1.22) deficiency, causing classical homocystinuria (HCU) (OMIM #236200), a disorder of methionine and homocysteine metabolism." (PMID 41464651, 2025). "We determined the variants in CBS gene in 14 Sri Lankan patients with homocystinuria, from 9 unrelated families." (PMID 39839200, 2025). "The correlation between genotype and phenotype in homocystinuria is complex, as specific mutations in the CBS gene can result in a wide spectrum of clinical manifestations." (PMID 39839200, 2025). "In a North Indian cohort of 14 patients with homocystinuria, Sanger sequencing of the CBS gene identified 15 distinct pathogenic or likely pathogenic variants, with compound heterozygosity observed in six patients." (PMID 39839200, 2025). "Summary of the characteristics of CBS variants detected in the present cohort of Sri Lankan children with homocystinuria." (PMID 39839200, 2025). "Homocystinuria due to cystathionine beta‐synthase [(CBS) (EC 4.2.1.22)] deficiency, also known as classic homocystinuria (OMIM: 236200), inherited as an autosomal recessive trait, is a disorder in the metabolism of sulphur‐containing amino acids." (PMID 39839200, 2025). "The spectrum of clinical features of homocystinuria due to CBS deficiency usually manifests in the first or second decade of life." (PMID 39839200, 2025). "CBS (cystathionine beta-synthase) is a key enzyme in the trans-sulphuration pathway; a deficiency of it is associated with homocystinuria." (PMID 40428427, 2025). "Although it was present in a heterozygous form, there are many reported cases of classical homocystinuria occurring in compound heterozygotes, and each of our patients has at least one or more additional mutations/polymorphisms in the CBS gene." (PMID 40650005, 2025). "The gene encodes cystathionine beta-synthase, and mutations in which cause homocystinuria, a multisystemic autosomal recessive disorder of the connective tissue, muscles, central nervous system (CNS), and cardiovascular system." (PMID 41510431, 2025). "In classical homocystinuria (HCU) due to the deficient activity of cystathionine β-synthase (CBS), elevated levels of homocysteine (Hcy) are linked to clinical manifestations." (PMID 40428324, 2025). "Phenotypic and genotypic characteristics of a cohort of Sri Lankan children with homocystinuria due to CBS deficiency." (PMID 39839200, 2025). "For instance, CBS is involved in homocysteine metabolism, and its disruption leads to homocystinuria, often associated with pectus excavatum, a feature also observed in our case." (PMID 41510431, 2025). "Overall, we revealed the clinical manifestations of two patients with homocystinuria and conclude that the compound heterozygous mutation of CBS gene is the cause of the disease." (PMID 40299504, 2025). "Cystathionine β‐synthase (CBS) deficiency is a rare autosomal recessive disorder also known as classical homocystinuria (OMIM 236200)." (PMID 40095936, 2025).
homocystinuria (continued). "At present, more than 200 CBS mutations have been reported to be causally associated with classical homocystinuria (HGMD Professional® 2024.1 total; The Human Gene Mutation Database, 2019)." (PMID 40299504, 2025). "CBS is the rate-limiting enzyme of the transsulfuration pathway utilizing homocysteine, and its deficiency is one of the common forms of hereditary homocystinuria in humans." (PMID 39595556, 2024). "To date, a diverse array of mutations has been identified in the CBS gene, contributing to the pathogenesis of CBS deficiency." (PMID 38790892, 2024). "Cystathionine β-synthase (CBS)-deficient homocystinuria (HCU) is an inborn error of sulfur amino acid metabolism inherited as an autosomal recessive trait." (PMID 38843767, 2024). "Classical homocystinuria has been recognised as a protein misfolding disorder as many of the known pathogenic mutations result in aggregation and degradation of the CBS enzyme." (PMID 38575566, 2024). "CBS deficiency represents a major challenge in the field of hereditary metabolic disorders and is often manifested by homocystinuria, a condition characterized by elevated homocysteine levels in the blood and urine." (PMID 38790892, 2024). "Understanding the structure and function of the CBS protein is essential for elucidating the pathophysiology of CBS deficiency and developing targeted therapeutic interventions." (PMID 38790892, 2024). "Classic homocystinuria is an inborn error of metabolism caused mainly by missense mutations leading to misfolded and/or unstable human cystathionine β-synthase (CBS) protein, causing the accumulation of excess total homocysteine (tHcy) in tissues." (PMID 37319242, 2023). "CBS is the single most common locus of mutations associated with homocystinuria, and, in this study, we have characterized three clinical variants (K384E/N and M391I), which reside in the linker region." (PMID 37949228, 2023). "Previously, it has been shown that certain missense containing human CBS proteins can be functionally rescued in mouse models of CBS deficiency by treatment with proteasome inhibitors." (PMID 37319242, 2023). "Hereditary mutations in CBS lead to homocystinuria, an autosomal recessive disorder (OMIM 236200) that affects four major organ systems: CNS, ocular, vascular and skeletal." (PMID 37949228, 2023). "The focus of this discussion will be on classic homocystinuria, which results from pathogenic variants in CBS, the gene encoding cystathionine β-synthase (CBS)." (PMID 37994477, 2023). "Pathogenic variants affecting CBS function lead to Hcy accumulation in both blood and urine, termed homocystinemia and homocystinuria, respectively." (PMID 37994477, 2023). "Cystathionine beta synthase (CBS) deficiency (also called classical homocystinuria) is the most common inborn error of sulfur amino acid metabolism, with an estimated prevalence of about 1/100,000 births world-wide." (PMID 37319242, 2023). "Classic homocystinuria shows autosomal recessive inheritance and is caused by biallelic pathogenic variants in CBS." (PMID 37994477, 2023). "CBS-deficient homocystinuria is chiefly caused by pathogenic missense mutations leading to conformational instability, misfolding and ultimately degradation of CBS." (PMID 35864237, 2022). "Cystathionine β-synthase (CBS) deficiency, also known as classical homocystinuria (HCU), is caused by biallelic mutations in the CBS gene." (PMID 34121999, 2021). "The main genetic causes of homocystinuria are cystathionine beta-synthase (CBS) deficiency and the remethylation defects." (PMID 33691747, 2021). "Deficiency of CBS is the most common cause of homocystinuria, an inherited metabolic disease with an impact on almost all human organs." (PMID 34356298, 2021). "As was the case with CBS variants in homocystinuria patients, variants in human CγL show loss of affinity for PLP." (PMID 34251022, 2021).
homocystinuria (continued). "A missense variant (NM_000071.3: c.253G>A) was identified in the CBS gene responsible for symptoms of classical homocystinuria." (PMID 34342182, 2021). "One example would be a deficiency in cystathionine-β-synthase (CBS), which is seen in classical homocystinuria." (PMID 34568401, 2021). "To date, 198 CBS allelic variants have been reported for classical homocystinuria (HGMD Professional ® 2020.3 total; The Human Gene Mutation Database, 2019)." (PMID 34342182, 2021). "Homocystinuria is a metabolic disorder caused by a deficiency of cystathionine beta-synthase with autosomal recessive inheritance." (PMID 34079667, 2021). "Homocystinuria (MIM# 236200) is the autosomal recessive metabolic genetic disorder due to the deficiency of cystathionine‐β‐synthase (CBS) enzyme." (PMID 34342182, 2021). "Ectopia lentis is the common ocular manifestation of homocystinuria resulting from cystathionine beta-synthase (CBS) deficiency which has a high risk of thromboembolic complications." (PMID 33985475, 2021). "Our study identified the spectrum of variants prevailing in the CBS gene responsible for classical homocystinuria from India." (PMID 33057012, 2020). "Overall, homocystinuria caused by CBS deficiency is considered a relatively rare disease with an incidence rate varying from one in every 200,000 to 335,000 live births." (PMID 32245022, 2020). "Pathogenic missense CBS mutations causing homocystinuria were shown to decrease the affinity of the enzyme to the PLP cofactor causing lower saturation of the enzyme with the PLP, which results in impaired catalytic activity." (PMID 32365821, 2020). "Further complicating variant interpretation, a number of variants in the regulatory domain have previously been observed to render CBS biochemically hyperactive and yet paradoxically cause symptoms typical for CBS deficiency." (PMID 32000841, 2020). "This review aims to examine the mutations spectrum of the CBS gene in homocystinuria patients with a greater emphasis on those reported in the Middle East and North Africa (MENA) region." (PMID 32245022, 2020). "Since only early diagnosis and timely therapy can effectively prevent long-term complications in patients with homocystinuria, many newborn screening programs worldwide target CBS deficiency." (PMID 32000841, 2020). "Homocystinuria is an inborn error of metabolism due to the deficiency in cystathionine beta-synthase (CBS) enzyme activity." (PMID 32245022, 2020). "The three most frequent genetic causes of homocystinuria are severe MTHFR deficiency, CBS deficiency which is called classical homocystinuria and methylmalonic aciduria with homocystinuria cblC type." (PMID 32751132, 2020). "While in the transsulfuration pathway, genetic mutation in CBS gene leading to classical homocystinuria is the frequent genetic abnormality." (PMID 32751132, 2020). "For the last three decades, CBS inactivating mutations have been extensively studied in the context of causing homocystinuria." (PMID 32245022, 2020). "Biallelic pathogenic variants in CBS gene cause the most common form of homocystinuria, the classical homocystinuria (HCU)." (PMID 32232970, 2020). "In Palestinian Arab homocystinuria patients, six different CBS mutations, c.304A>C, c.833T>C, c.785C>G, g.1627del19, IVS17 (g18327del 5), and IVS4 (g6643del 29), have been reported in this highly inbred population." (PMID 32245022, 2020). "A large body of literature (approximately 300 articles) relates to the role of CBS mutations in the pathogenesis of classical homocystinuria, a rare inborn error of sulfur amino acid metabolism caused by the deficiency of CBS activity." (PMID 32365821, 2020). "There have been several decades of work related to inactivating CBS mutations as the cause of classical homocystinurias; novel approaches related to the experimental therapy of homocystinuria (e.g., enzyme replacement therapy) have now entered clinical trials." (PMID 32365821, 2020).
homocystinuria (continued). "In CBS deficiency, the conversion of Hcy to cystathionine is impaired, and CBS deficiency is known as classic homocystinuria or homocystinuria type I." (PMID 33239586, 2020). "Classical homocystinuria, characterized by elevated homocysteine in plasma and urine, is caused by variants in the cystathionine beta-synthase (CBS) gene, most of which are rare." (PMID 32000841, 2020). "Patients with CBS-deficient “classical” homocystinuria show a variety of clinical symptoms including atherothrombosis, mental retardation, osteoporosis, lens dislocation, and Marfan-like skeletal abnormality." (PMID 31319489, 2019). "We identified a DV found at a PPI interface, V180A of cystathionine β-synthase (CBS), which is associated with homocystinuria (MIM: 236200)." (PMID 31199866, 2019). "Taurine, a compound potentially reducing oxidative damage, is being tested in a clinical trial with homocystinuria (CBS-deficient) patients (NCT01192828)." (PMID 29743968, 2018). "Inactivating mutations in CBS contribute to the pathogenesis of the autosomal recessive disease CBS-deficient homocystinuria." (PMID 30050925, 2018). "This group of diseases encompasses two distinctive clinical entities: classical homocystinuria due to cystathionine β-synthase (CBS) deficiency (transsulfuration pathway) and the rare inborn errors of cobalamin and folate metabolism (remethylation pathway)." (PMID 29743968, 2018). "This prompted us to investigate in the present study a reportedly mild pathogenic mutation associated with classical homocystinuria, a proline-to-leucine substitution at residue 49 in human CBS." (PMID 28421128, 2017). "A multitude of genes are related to homocystinuria, but mutations in the gene that encodes for CBS are the prevalent." (PMID 28774346, 2017). "The 146 C>T transition in exon 1 of the CBS gene generates the clinically relevant p.P49L variant, identified in patients with classical homocystinuria." (PMID 28421128, 2017). "Classical homocystinuria is an inborn error of metabolism associated with deficiency in cystathionine β-synthase (CBS), a key enzyme in the transsulfuration pathway of methionine metabolism." (PMID 28421128, 2017). "Classical homocystinuria (OMIM #236200) is an inborn error of metabolism associated with mutations in the CBS gene." (PMID 28421128, 2017). "Mutations in the CBS gene lead to homocystinuria characterized by elevated plasma Hcy and cognitive durability." (PMID 28649192, 2017). "Some of these variants were seen in multiple individuals, in particular 5/31 (patients 43, 49, 54, 62, 71) are carriers of the mild pyridoxine responsive CBS p.I278T variant associated with homocystinuria." (PMID 28750028, 2017). "Mutations in the CBS gene can lead to classical homocystinuria, a human disease associated with oxidative stress that affects the vascular, neurological, and skeletal systems." (PMID 28421128, 2017). "Severe hHcy occurs in homocystinuria, an innate metabolic disorder characterized by a deficiency of CBS enzyme activity." (PMID 27775595, 2016). "CBS deficiency in humans has several severe symptoms, including homocystinuria and mental retardation, among others." (PMID 26462863, 2016). "Patients with severe hHcy occur in homocystinuria, an inherited metabolic disorder characterized by a deficiency of CBS enzyme activity." (PMID 27775595, 2016). "In this study, we characterized the clinical manifestations and investigated the molecular basis of a Han Chinese family with homocystinuria, to expand the CBS mutation spectrum of the homocystinuric patients from China." (PMID 26667307, 2015). "In order to better understand homocystinuria pathogenesis, functional studies are needed to illustrate the role of CBS and the underlying mechanisms of this disease." (PMID 26667307, 2015). "CBS deficiency, a main factor causing homocystinuria, is an autosomal recessively inherited genetic defect." (PMID 26667307, 2015).